Y_RNA (Y RNA )
Gene: Miscellaneous RNA gene on chromosome 10 (72,654,165 to 72,654,276, reverse strand). Ensembl gene ENSG00000201881.
Homologues: Orthologues: chimpanzee Y_RNA (100% identical), macaque Y_RNA (92% identical). Paralogues in human: Y_RNA (88% identical), RNY1 (86% identical), Y_RNA (86% identical), Y_RNA (85% identical), RNY1P11 (84% identical), Y_RNA (84% identical), Y_RNA (83% identical), Y_RNA (82% identical), Y_RNA (81% identical), RNY1P7 (80% identical), RNY1P8 (80% identical), Y_RNA (80% identical), and 96 more.